RNU7-156P (RNA, U7 small nuclear 156 pseudogene)
Gene: Small nuclear RNA gene on chromosome 5 (143,542,514 to 143,542,587, reverse strand). Ensembl gene ENSG00000253023.
Homologues: Orthologues: chimpanzee U7 (69% identical), macaque U7 (64% identical). Paralogues in human: RNU7-40P (62% identical), U7 (62% identical), RNU7-11P (61% identical), RNU7-181P (61% identical), RNU7-26P (61% identical), RNU7-62P (61% identical), RNU7-75P (61% identical), RNU7-1 (59% identical), RNU7-102P (59% identical), RNU7-24P (59% identical), RNU7-3P (59% identical), RNU7-43P (59% identical), and 142 more.